ROS1 (ROS proto-oncogene 1, receptor tyrosine kinase)
Diseases named in the same sentence as ROS1 in open-access papers (continued):
Sharing a sentence is not in itself a finding about the gene and the disease.
inflammatory breast carcinoma (3 papers, 2020 to 2023). An advanced, invasive breast adenocarcinoma characterized by the presence of distinct changes in the overlying skin. "Recently, ROS1 pathogenic somatic variants were identified in inflammatory breast cancer and ROS1 somatic mutations are present in the COSMIC database." (PMID 32906649, 2020).
intrahepatic cholangiocarcinoma (3 papers, 2015 to 2025). A carcinoma that arises from the intrahepatic bile duct epithelium in any site of the intrahepatic biliary tree. "ROS1 protein expression was associated with well-differentiated histology and better survival in patients with resected intrahepatic cholangiocarcinoma." (PMID 26475437, 2015). "ROS1 protein expression was associated with well-differentiated histology and better survival in our patients with resected intrahepatic cholangiocarcinoma." (PMID 26475437, 2015). "In terms of prognosis, higher ROS1 expression has been shown to confer a protective prognostic effect in cases of intrahepatic cholangiocarcinoma and invasive ductal carcinoma of the breast." (PMID 40847660, 2025). "We investigated the clinical and pathological significance of ROS1 expression in intrahepatic cholangiocarcinoma." (PMID 26475437, 2015). "In another report, ROS1 fusion was found in 14–16 % of patients with gallbladder carcinoma or extrahepatic cholangiocarcinoma, but not those with intrahepatic cholangiocarcinoma." (PMID 26475437, 2015). "We could not find any ROS1 rearrangement by FISH in 102 Korean patients with intrahepatic cholangiocarcinoma." (PMID 26475437, 2015).
liver cancer (3 papers, 2015 to 2022). An epithelial or non-epithelial malignant neoplasm that arises from the liver. "ROS1-expressing tumors were more frequent in periductal (50.0 %) or intraductal type (66.7 %) than mass forming type (31.6 %) as characterized according to the histologic subtypes proposed by the Liver Cancer Study Group of Japan." (PMID 26475437, 2015).
lymph node metastases (3 papers, 2016 to 2025). "In terms of metastasis patterns, patients with ROS1 and RET fusions had a significantly higher incidence of distant lymph node metastases than patients with EGFR mutations (ROS1+ vs. EGFR+, 11.6% vs. 2.9%, p = 0.036; RET+ vs. EGFR+, 18.2% vs. 2.9%, p = 0.048)." (PMID 40751559, 2025).
neuroblastoma (3 papers, 2013 to 2023). Neuroblastoma (NB) is the most common solid, extracranial childhood tumor. "In vitro and in vivo growth of TRK-A-dependent IMR-32 neuroblastoma cells and ROS1-overexpressing NIH3T3 cells were inhibited by GTx-186." (PMID 24386191, 2013).
papillary thyroid cancer (3 papers, 2018 to 2025). "Genes less commonly rearranged in papillary carcinoma with BRAF V600E-like signature include BRAF, MET and ROS1 (e.g., CUL1-BRAF, MKRN1-BRAF, SND1-BRAF, TTYH3-BRAF CCDC30-ROS1 EML4-MET, and TFG-MET)." (PMID 41175860, 2025).
skin cancer (3 papers, 2020 to 2025). "In the 4th edition of the 2018 WHO classification of skin tumors, lesions in the spitzoid pathway (pathway 4) are characterized by mutations in HRAS, tyrosine kinase fusions (ALK, ROS1, RET, NTRK1/3, and MET), or serine-threonine kinase fusions (BRAF, MAP3K8)." (PMID 33040161, 2021).
acral lentiginous melanoma (2 papers, 2018 to 2019). A form of melanoma occurring most often on the plantar, palmar, subungual, and periungual skin. "One patient with heavily pretreated acral lentiginous melanoma carrying a ROS1-GOPC fusion was treated with entrectinib (TKI with activity against tropomyosin receptor kinase (Trk), ROS1 and ALK), leading to a PR with 38% reduction in tumor burden at 3 months and 55% at 11 months." (PMID 30719217, 2019).
bladder cancer (2 papers, 2007 to 2013). "Samples from cancers of the urinary bladder (3 samples) and esophagus (4 samples) expressed both TRK-A and ROS1, which could potentially lead to additive or synergistic proliferation." (PMID 24386191, 2013).
cervical cancer (2 papers, 2023 to 2024). A primary or metastatic malignant neoplasm involving the cervix. "In this study, we performed RNA sequencing of 116 cervical cancer samples and detected four cases with fusion genes involving FGFR3 or ROS1 as potential therapeutic targets." (PMID 37537783, 2023).
colorectal tumors (2 papers, 2018 to 2023). "There were no instances of MSI in 56 non-colorectal tumors carrying ALK, ROS1, RET or NTRK1 rearrangements." (PMID 37686416, 2023).
coronary artery disease (2 papers, 2012 to 2013). "Intriguingly, single nucleotide polymorphism (SNP) variants in ROS1 have been associated with increased risk of vascular diseases, including coronary artery disease and stroke." (PMID 23637631, 2013).
fibrosarcoma (2 papers, 2020 to 2022). A malignant mesenchymal fibroblastic neoplasm affecting the soft tissue and bone. "Such treatments were considered in 15 of the 23 NSCLC dossiers for the following mutations: anaplastic lymphoma kinase (ALK), rapidly accelerated fibrosarcoma-isoform B (BRAF), epidermal growth factor receptor (EGFR) and the C-ros oncogene 1 (ROS1)." (PMID 32236766, 2020).
fungal infection (2 papers, 2017 to 2023). "A. thaliana requires ROS1, DML2, and DML3 to mount an immune response to Pseudomonas syringae infection, while in potato, ROS1 is elevated in response to β-aminobutyric acid, a pathogen signaling molecule that primes plant cells to fungal infection." (PMID 37834194, 2023).
infertile (2 papers, 2019 to 2025). "ROS1-deficient mice have been found infertile, which is induced by differentiation of epididymal epithelial cells causing maturation in defective sperms." (PMID 31138757, 2019). "ROS1 is expressed in the initial segment (IS) of the epididymis in mice, and Ros1 knockout (KO) male mice are infertile due to abnormal epithelium differentiation of the IS and impaired sperm maturation." (PMID 39568175, 2025).
male infertility (2 papers, 2024 to 2025). The inability of the male to effect fertilization of an ovum after a specified period of unprotected intercourse. "An intriguing question is whether dysfunction of NELL2, NICOL, or ROS1 causes male infertility, although mutations in these genes have not been identified as causal factors in humans." (PMID 38169386, 2024). "No obvious abnormalities other than male infertility were observed in Ros1 KO mice, but it is unclear whether specific ROS1 inhibition has adverse effects in humans." (PMID 39568175, 2025).
meningioma (2 papers, 2018 to 2024). A generally slow growing tumor attached to the dura mater. "The use of ROS1 inhibitors in ROS1-positive patients has yielded promising results, extending survival in cases like atypical meningioma and lung blastoma." (PMID 38273343, 2024).
mesenchymal tumor (2 papers, 2023). "To date, no increased copy numbers of ROS1 gene had reported in English literature in human tumors including cancer and mesenchymal tumor, nor ROS1 re-arrangement in RMS including ES-RMS." (PMID 36998041, 2023).
mucinous adenocarcinoma (2 papers, 2015 to 2025). An invasive adenocarcinoma composed of malignant glandular cells which contain intracytoplasmic mucin. "Specifically, papillary or mucinous carcinomas were strongly related to expression of the ROS1 protein (73.3 %)." (PMID 26475437, 2015). "Furthermore, CD74-ROS1 is the most common form of ROS1 fusion in NSCLC, and CD74-NRG1 gene fusion activates genomic alterations in aggressive mucinous adenocarcinomas, offering potential therapeutic opportunities for lung tumor subtypes that have not yet been effectively treated." (PMID 40470045, 2025).
oral cancer (2 papers, 2020). "In summary, our results demonstrate that oncogenic ROS1 is present in mitochondria, governs mitochondrial morphogenesis, and confers metabolic plasticity to promote oral cancer invasiveness." (PMID 33019722, 2020). "We previously showed that upregulation of ROS1 oncogene leads to oral cancer metastasis." (PMID 33019722, 2020).
oral squamous cell carcinoma (2 papers, 2020 to 2022). "Increased ROS proto-oncogene 1 (ROS1) expression has been implicated in the invasiveness of human oral squamous cell carcinoma (OSCC)." (PMID 33019722, 2020).
sarcomatoid carcinoma (2 papers, 2025). A malignant epithelial neoplasm characterized by the presence of spindle cells and anaplastic morphologic features. "The oncogenic potential of TPM3‐ROS1 is further supported by its role in spindle cell carcinoma (SpCC) of the lung, where targeted therapy with crizotinib, a ROS1 inhibitor, has shown clinical efficacy." (PMID 41275415, 2025).
spindle cell neoplasm (2 papers, 2023 to 2025). A benign or malignant neoplasm characterized by the presence of neoplastic spindle cells. "IMT is a low-grade spindle cell neoplasm typically associated with anaplastic lymphoma kinase (ALK) and more rarely with ROS oncoprotein (ROS1) or neurotrophic tropomyosin kinase receptor (NTRK) rearrangements and a less aggressive clinical course compared to DDLPS." (PMID 40211332, 2025). "ES-RMS with TFCP2 rearrangement is a rare malignant tumor and easily confused with other epithelioid or spindle cell tumors, it may harbor additional gene alteration in addition to TFCP2 rearrangement, such as MET mutation, increased copy numbers of EWSR1 and ROS1 gene, high TMB." (PMID 36998041, 2023).
thymic carcinoma (2 papers, 2017 to 2022). Thymic carcinoma (TC) is a type of thymic epithelial neoplasm characterized by a high malignant potential. "In this study, frequently mutated genes in thymic carcinomas included KIT, DDR2, PDGFRA, ROS1, and IGF1R." (PMID 35884448, 2022). "Immunohistochemistry was performed to study the expression of ALK, HER2, HER3, MET, phospho-mTOR, p16INK4A, PDGFRA, PDGFRB, PD-L1, PTEN and ROS1 in type A and B3 thymomas and thymic carcinomas." (PMID 27844328, 2017). "Type A and B3 thymoma and thymic carcinoma tissues were stained with antibodies to ALK, HER2, HER3, MET, phospho-mTOR, PDGFRA, PDGFRB, PD-L1, p16INK4A, PTEN and ROS1 to identify potential targets for therapy." (PMID 27844328, 2017). "Type B3 thymomas and thymic carcinomas did not express ROS1." (PMID 27844328, 2017).
adenocarcinoma in situ (1 paper, 2023). A lesion in which the normally situated glands are partially or completely replaced by atypical cells with malignant characteristics. "There were 2 cases of ROS1‐positive GGO, 1 case of adenocarcinoma in situ and 1 case of invasive adenocarcinoma with acinar‐like growth type." (PMID 37340599, 2023).
aortic coarctation (1 paper, 2023). "For example, cardiotoxicity caused by ALK, ROS1, EGFR-TKIs; aortic coarctation caused by VEGF-TKI; pulmonary hypertension caused by ALK-TKI, interstitial pneumonia caused by EGFR/ALK TKIs, infection caused by BTK inhibitors and other adverse reactions." (PMID 36761953, 2023).
breast adenocarcinoma (1 paper, 2023). "Of note, ROS1+ breast adenocarcinoma, although with limited number of samples, had a tenfold lower junction reads than those of ROS1+ NSCLC." (PMID 37853341, 2023). "Of note, ROS1+ breast adenocarcinoma, though with limited number of samples, had a tenfold lower junction reads than those of ROS1+ NSCLC." (PMID 37853341, 2023). "Additionally, two ROS1+ breast adenocarcinoma had fusion breakpoints at exon 17 and exon 27, respectively." (PMID 37853341, 2023). "ROS1+ breast adenocarcinoma was the third most common ROS1+ solid tumors but only at 3%." (PMID 37853341, 2023).
cardiac conduction disease (1 paper, 2024). "Results from another previous pharmacovigilance analysis also revealed that ALK and ROS1 inhibitors induced higher odds of cardiac conduction disease than other targeted therapies." (PMID 38357305, 2024).
COVID-19 (1 paper, 2020). A disease caused by infection with severe acute respiratory syndrome coronavirus 2. "One case of each EGFR, ALK, ROS1, and BRAF genetic alteration were found in the COVID-19 patients." (PMID 33042826, 2020).
cyst (1 paper, 2022). A sac-like closed membranous structure that may be empty or contain fluid or amorphous material. "Consistent with the contrasting expression patterns, the mutant alleles of ROS1, DML2, and DML3 showed opposite responses to infection by cyst and root-knot nematodes." (PMID 36704169, 2022).
diffuse astrocytoma (1 paper, 2023). A low-grade (WHO grade II) astrocytic neoplasm. "These include diffuse astrocytoma, MYB- or MYBL1-altered; diffuse low-grade glioma, MAPK pathway-altered; polymorphous low-grade neuroepithelial tumor of the young (BRAF mutations and FGFR2 fusions); and infant-type hemispheric glioma (alterations in NTRK, ROS1, ALK, or MET)." (PMID 37509316, 2023).
Disseminated intravascular coagulation (1 paper, 2022). Disseminated intravascular coagulation is characterized by the widespread activation of coagulation, which results in the intravascular formation of fibrin and ultimately thrombotic occlusion of small and midsize vessels. "Several authors reported a heightened thromboembolic risk of ROS-1-rearranged tumors compared with NSCLCs harboring non-rearranged ROS-1, and even rarer cases of thrombotic microangiopathies and disseminated intravascular coagulation." (PMID 35200557, 2022).
emphysema (1 paper, 2022). "In this study, compared with non‐ALK&ROS1/EGFR mutations in NSCLC patients, patients with EGFR mutation had a lower incidence of pulmonary emphysema." (PMID 35081265, 2022). "In the ALK&ROS1‐positive group, the most were female (χ2 = 7.644, P = 0.008) patients, and proportion of patients with emphysema was lower (χ2 = 8.202, P = 0.003) than the ALK&ROS1‐negative group." (PMID 35081265, 2022).
Fusarium infection (1 paper, 2017). "Similar to Fusarium infection and gene expression analysis, DNA methylation analysis showed that loss of ROS1 results in hypermethylation of promoter TE sequences, whereas DNA methylation profiles of dml2-1 and dml3-1 were virtually identical to those of the WT Col-0 plants." (PMID 28894455, 2017). "Suppressed gene expression under mock conditions and reduced gene induction upon Fusarium infection, characteristic of the rdd mutant, was largely replicated in the ros1-3 mutant." (PMID 28894455, 2017). "ros1, dml2, and dml3 were previously shown to have some functional redundancy in the response of Arabidopsis to Fusarium infection." (PMID 28894455, 2017).
gynecologic cancers (1 paper, 2025). "Evidence on the pathognomic role of ROS1 alterations (fusions, overexpression, or mutations) in other tumor types supports their potential as a prognostic and treatment target warranting investigation in gynecologic cancers as well." (PMID 40847660, 2025).
IgG4-related disease (1 paper, 2023). "All 56 IgG4-related disease subjects were negative for ALK and ROS1 on immunohistochemical analysis; 6 subjects were negative on the fusion assay." (PMID 37685395, 2023).
insulinoma (1 paper, 2023). "This patient’s tumor is the first malignant insulinoma to our knowledge to possess simultaneous mutations in ATRX, ROS1, and KMT2A." (PMID 36835815, 2023).
invasive lobular carcinoma (1 paper, 2023). "MYOD1 amplification was reported to be of pronostic interest in BC, with the greatest prevalence in breast invasive lobular carcinoma as well as ROS1 amplification." (PMID 38137385, 2023).
juvenile myelomonocytic leukemia (1 paper, 2022). A myelodysplastic/myeloproliferative neoplasm of childhood that is characterized by proliferation principally of the granulocytic and monocytic lineages. "In a genomic study of patients with juvenile myelomonocytic leukemia (JMML), 16 patients had no RAS variants, and in three of these that were 56 months of age or older, the researchers identified ALK/ROS1 tyrosine kinase fusions (DCTN1-ALK, RANBP2-ALK, and TBL1XR1-ROS1)." (PMID 36295546, 2022).
Langerhans cell histiocytosis (1 paper, 2023). Langerhans cell histiocytosis (LCH) is a systemic disease associated with the proliferation and accumulation (usually in granulomas) of Langerhans cells in various tissues. "To the best of our knowledge, we reported here the first case of successful disease control using entrectinib treatment in non-Langerhans cell histiocytosis with novel ROS1::GIT2 fusion." (PMID 36416966, 2023). "Here, we report a pediatric case of non-Langerhans cell histiocytosis affecting the CNS and harboring a novel ROS1 fusion (ROS1::GIT2) identified by comprehensive genomic profiling (CGP), representing a previously unrecognized association." (PMID 36416966, 2023).
lymphoid neoplasm (1 paper, 2025). A neoplasm composed of a lymphocytic cell population which is usually malignant (clonal) by molecular genetic and/or immunophenotypic analysis. "Mutations in EGFR (p.V843I; COSV51767379) and ROS1 (p.R2269Q; COSV63862037) have been extensively documented in solid tumors, although they have been reported anecdotally in lymphoid neoplasms for ROS1 (COSMIC database)." (PMID 40067847, 2025).
mesoblastic nephroma (1 paper, 2021). A solid, unencapsulated tumor of the kidney composed of spindle mesenchymal cells that resemble fibroblasts or muscle cells. "For example, in recent years targetable fusions have been identified with high frequency in select pediatric tumors (i.e. NTRK‐fusions in infantile fibrosarcoma and mesoblastic nephromas or ALK/ROS1/NTRK3 fusions in infantile myofibroblastic tumors)." (PMID 33751835, 2021).
mesothelioma (1 paper, 2018). A usually malignant and aggressive neoplasm of the mesothelium which is often associated with exposure to asbestos. "To assess the frequency of co-activation in primary mesotheliomas, we examined the co-expression of mTOR and ALK, ROS1, and MET at both mRNA and protein levels in tumor samples by qRT-PCR and IHC, respectively." (PMID 29755689, 2018).
metastatic cancer (1 paper, 2023). A carcinoma which has spread from the original site of growth to another anatomic site. "The studies evaluated both the safety and efficacy of orally administering entrectinib to adults with locally advanced metastatic cancer with NTRK1, NTRK2, NTRK3, ROS1, or ALK rearrangements." (PMID 37111737, 2023). "The ALKA-372-001, STARTRK-1, and STARTRK-2 studies evaluated both the safety and efficacy of orally administering entrectinib to adult patients with locally advanced metastatic cancer with NTRK1, NTRK2, NTRK3, ROS1, or ALK rearrangements." (PMID 37111737, 2023).
mucinous tumors (1 paper, 2015). "Microscopic features of tumors with ROS1 expression were significantly related to well differentiated histology, papillary or mucinous tumors, and intestinal type." (PMID 26475437, 2015).
ocular tumors (1 paper, 2025). "If ROS1-positivity is detected, it will further confirm the therapeutic mechanism of entrectinib in suppressing ocular tumors." (PMID 41140667, 2025).
ovarian tumor (1 paper, 2023). "Zhai and colleagues reported that APG-2449, a novel ALK/ROS1/FAK inhibitor, is effective against human ovarian tumor either alone or in combination with other therapies." (PMID 37875515, 2023).
pericardial effusion (1 paper, 2022). Fluid collection within the pericardial sac, usually due to inflammation. "In one pericardial effusion, ROS1, was positive in ICC, but the FISH result showed a loss of signal in 66% of the nuclei." (PMID 36142468, 2022).
pilocytic astrocytoma (1 paper, 2024). Pilocytic astrocytoma is a rare subtype of low-grade glioma of the central nervous system characterized by a well circumscribed, often cystic, brain tumor with a discrete mural nodule and long, hair-like projections that extend from the neoplastic astrocytes. "Based on morphology, immunohistochemistry and molecular and epigenetic data the diagnosis of a pilocytic astrocytoma (CNS WHO grade 1) with an ROS1 fusion was established." (PMID 39409964, 2024). "Regarding the ROS1 fusions, our case with GOPC-ROS1 fusion exhibited an LG morphology, most closely resembling pilocytic astrocytoma." (PMID 39409964, 2024). "However, ROS1 gene fusions can also appear in cases that are morphologically and (epi)genetically pilocytic astrocytoma or IDH-wildtype glioblastoma." (PMID 39409964, 2024).